NAT10 (N-acetyltransferase 10)
Diseases named in the same sentence as NAT10 in open-access papers (continued):
Sharing a sentence is not in itself a finding about the gene and the disease.
colon cancer (continued). "In comparison to the adjacent normal tissues, the expression of NAT10 in colon tumor tissues was significantly increased." (PMID 38243170, 2024). "We also detected the expression levels of the mismatch repair proteins after overexpression and knockdown of NAT10 in colon cancer cell lines." (PMID 36908042, 2023). "Subsequently, we divided the colon cancer samples into two groups, namely the high NAT10 expression group and the low NAT10 expression group." (PMID 36908042, 2023). "The knockdown of NAT10 promotes ferroptosis and inhibits proliferation and metastasis in colon cancer cells, which can be reversed by ferroptosis inhibition both in vitro and in vivo." (PMID 37371948, 2023). "Next, we divided colon cancer patients into the NAT10 high expression and NAT10 low expression groups." (PMID 36908042, 2023). "In vitro experiments also showed that NAT10 can significantly affect colon cancer cell proliferation." (PMID 36908042, 2023). "We collected 24 normal and 24 colon cancer tissue specimens to verify the expression of NAT10 in colon cancer." (PMID 36908042, 2023). "Using the intersection of differential genes between the NAT10 high expression and NAT10 low expression groups and between colon cancer tissue and normal tissue, we identified 106 acetylation- related differential genes." (PMID 36908042, 2023). "In conclusion, we verified that NAT10 plays an important role in colon cancer using databases and in vitro experiments." (PMID 36908042, 2023). "CCK8 results showed that colon cancer cell proliferation was significantly enhanced after NAT10 overexpression." (PMID 36908042, 2023). "NAT10 catalyzes N4-acetylcytidine (ac4C) deposition on different RNA substrates and is involved in colon cancer invasion and metastasis." (PMID 36553667, 2022). "The inhibitory effect of FSP1 on ferroptosis may play an important role in the NAT10‐mediated promotion of colon cancer cell proliferation, migration, and invasion." (PMID 39817252, 2025). "Subsequently, we detected ac4C modification and NAT10 levels in colon cancer cells." (PMID 41426311, 2025). "NAT10 promotes cancer progression by catalyzing ac4C production on mRNAs, but it remains unclear whether emodin regulates glycolysis in colon cancer cells by targeting NAT10." (PMID 41426311, 2025). "In addition, NAT10 was shown to promote the maintenance of stemness among colon cancer cells and enhance chemical resistance by stabilizing NANOGP8 mRNA." (PMID 40606759, 2025). "In both colon cancer cell lines (HT-29 and LoVo), downregulation of NAT10 impaired the proliferative, migratory, invasive, tumor-forming, and metastatic abilities of these cells; conversely, excess NAT10 expression promoted these abilities." (PMID 41316475, 2025). "Additionally, our results demonstrated that emodin inhibited ac4C modification and NAT10 expression in colon cancer cells." (PMID 41426311, 2025). "In addition, transmission electron microscopy of these cells showed that the mitochondrial matrix condenses and forms enlarged cristae, suggesting knocking down NAT10 induces ferroptosis in colon cancer cells." (PMID 38233930, 2024). "In addition, NAT10 is involved in colon cancer cell metastasis; down-regulating NAT10 inhibits cell migration and reduces the number of aggressive cancer cells." (PMID 38233930, 2024). "Although NAT10 expression did not appear to be an independent prognostic factor according to Cox regression analysis, the Kaplan‒Meier curve indicated that individuals with elevated NAT10 expression levels experienced reduced overall survival rates among colon cancer patients." (PMID 38243170, 2024). "In addition, we observed a trend toward a higher incidence of high NAT10 expression among colon cancer patients with positive PD-L1 expression, despite the lack of statistical significance." (PMID 38243170, 2024). "Conversely, NAT10 inhibits cell proliferation in colon cancer." (PMID 38182571, 2024).
colon cancer (continued). "Immunohistochemical staining indicated that NAT10 was highly expressed in colon cancer tissues." (PMID 36908042, 2023). "NAT10 is highly expressed in colon cancer tissues and promotes colon cancer proliferation." (PMID 36908042, 2023). "Our study showed that NAT10 is highly expressed in human colon cancer tissues." (PMID 36908042, 2023). "Moreover, NAT10 overexpression restored glycolysis in colon cancer cells inhibited by emodin." (PMID 41426311, 2025). "In addition, NAT10 promotes development of colon cancer by affecting ferroptosis." (PMID 39251905, 2024). "Therefore, NAT10 may be a promising prognostic and therapeutic target in colon cancer by regulating FSP1 mRNA stability and ferroptosis." (PMID 37371948, 2023). "In colon cancer, miR-6716-5p interacts with the 3′UTR of NAT10 mRNA, resulting in decreased NAT10 protein levels and affecting the progression of the disease." (PMID 40881352, 2025). "However, whether NAT10 mediates colon cancer development through glycolysis remains unclear." (PMID 41426311, 2025). "NAT10 expression is upregulated in both colon cancer (COAD) tissues and multiple colon cancer cell lines." (PMID 41316475, 2025). "NAT10 can increase NANOGP8 ac4C modification levels and support NANOGP8 mRNA stability in colon cancer to maintain stemness and resist chemotherapy." (PMID 41316475, 2025). "However, whether PGK1 is mediated by NAT10 in colon cancer remain unclear." (PMID 41426311, 2025). "In this study, we demonstrated that NAT10 stabilized PGK1 mRNA through enhanced ac4C modification on PGK1, thereby promoting glycolysis and cell proliferation in colon cancers." (PMID 41426311, 2025). "In conclusion, we demonstrated that emodin inhibited tumor growth of colon cancer by suppressing glycolysis in tumor cells through inhibiting NAT10-mediated ac4C modification of PGK1, indicating that emodin is an effective medicine for treatment of colon cancer." (PMID 41426311, 2025). "Next, we validated the high expression of NAT10 in colon cancer cell lines HT29, HCT116, SW480, and DLD1, compared with normal intestinal mucosal epithelial cell line NCM460." (PMID 36908042, 2023). "In addition, NAT10 plays a key role in COAD development by influencing the stability and iron efflux of FSP1 mRNA, indicating that it could be a new prognostic and therapeutic target for colon cancer." (PMID 41316475, 2025).
cervical carcinoma (17 papers, 2022 to 2025). A carcinoma arising from either the exocervical squamous epithelium or the endocervical glandular epithelium. "In cervical cancer tissues, NAT10 expression is significantly increased, which is associated with poor clinical prognosis." (PMID 39764566, 2025). "Recent research on NAT10‐catalyzed ac4C modifications in immune dysregulation and tumor immunotherapy response has found that NAT10 is significantly upregulated in cervical cancer and is associated with poorer survival in cervical cancer patients." (PMID 39764566, 2025). "In this work, we found that in cervical cancer, NAT10 is markedly over-expressed and thus is tightly linked with poor prognosis in patients with cervical cancer." (PMID 37484809, 2023). "In conclusion, our study revealed that the ac4C regulator NAT10 is not only positively associated with poor prognosis of cervical cancer, but also promotes tumorigenesis in vitro and in vivo." (PMID 37484809, 2023). "In cervical cancer, NAT10/ac4C/FOXP1 induced the expression of GLUT4 and KHK, thereby promoting glycolytic metabolism and immune suppression." (PMID 39143228, 2025). "Studies have shown that NAT10 promotes the progression of various malignant tumor diseases, such as colorectal, breast, and cervical cancer." (PMID 41189569, 2025). "Studies in cervical cancer also demonstrated that NAT10 enhances HNRNPUL1 mRNA stability through ac4C modification, thereby promoting cancer cell proliferation, invasion, and migration." (PMID 40881352, 2025). "Downregulation of NAT10 inhibits the proliferative, invasive, and migratory capabilities of cervical cancer and oral squamous cell carcinoma cells." (PMID 41316475, 2025). "Through RNA sequencing (RNA-seq) and acetylated RNA immunoprecipitation sequencing (acRIP-seq) analysis, HNRNPUL1 was identified as a target of NAT10 in cervical cancer." (PMID 41316475, 2025). "CircMAST1 competitively sequesters NAT10 and blocks Yes-associated protein (YAP) ac4C modification, thereby promoting its degradation and suppressing tumor progression in cervical cancer." (PMID 41316475, 2025). "The NAT10 protein regulates HNRNPUL1 expression in cervical cancer cells by catalyzing ac4C formation and increasing the stability of HNRNPUL1 mRNA." (PMID 38233930, 2024). "HOXC8/NAT10/FOXP1 promotes progression of cervical cancer and formation of suppressive immune microenvironment by regulating glucose metabolism." (PMID 39640362, 2024). "Recent evidence shows that the target of NAT10 in cervical cancer is heterogeneous nuclear ribonucleoprotein U like 1 (HNRNPUL1)." (PMID 38233930, 2024). "In cervical cancer, NAT10 overexpression induces HNRNPUL1 and DDR1 mRNA expression by promoting acetylation, enhancing tumor proliferation, invasion, and metastasis." (PMID 38233930, 2024). "A database analysis was conducted to study the relationship between NAT10 and the malignant behavior of cervical cancer cells." (PMID 38233930, 2024). "The purpose of this report was to explore the role and mechanism of NAT10-mediated ac4C modification in cervical cancer." (PMID 37484809, 2023). "Currently, the role of NAT10-mediated RNA acetylation modification in cervical cancer remains to be elucidated." (PMID 37484809, 2023). "Two GEO datasets (GSE6791 and GSE 75132), we noticed that NAT10 is significantly up-regulated in cervical cancer compared to normal cervical epithelial tissue." (PMID 37484809, 2023). "On the basis of transcriptome analysis of TCGA and GEO open datasets (GSE52904, GSE29570, GSE122697), NAT10 is upregulated in cervical cancer tissues and correlated with poor prognosis." (PMID 37484809, 2023). "In conclusion, this work shows the essential role of the NAT10-ac4C-HNRNPUL1 axis in cervical cancer progression." (PMID 37484809, 2023). "In this work, we revealed that overexpression of NAT10 is coupled with low prognosis in cervical cancer patients and that NAT10 suppresses tumorigenesis in cervical cancer." (PMID 37484809, 2023).
cervical carcinoma (continued). "Currently, RNA ac4C modification mediated by NAT10 in cervical cancer development is primarily unresolved." (PMID 37484809, 2023). "Next, we examined NAT10 expression in cervical cancer in the Genotype-Tissue Expression (GTEx) project and the Cancer Genome Atlas (TCGA) dataset." (PMID 37484809, 2023). "In contrast, the knockdown of NAT10 suppressed the migration and invasive potential of cervical cancer cells, but the up-regulation of HNRNPUL1 partially reversed these effects." (PMID 37484809, 2023). "This study illustrates the oncogenic role of NAT10 in cervical cancer (CCa) and elucidates the mechanism by that the NAT10/ac4C/FOXP1 axis functions to accelerate glycolysis and promote infiltration of immunosuppressive Tregs into TME." (PMID 37818745, 2023). "Combined RNA-seq and acRIP-seq analysis revealed HNRNPUL1 as the target of NAT10 in cervical cancer." (PMID 37484809, 2023). "HNRNPUL1 overexpression partially restored cellular function in cervical cancer cells with NAT10 knockdown." (PMID 37484809, 2023). "Knockdown of NAT10 suppressed the cell proliferation, invasion, and migration of cervical cancer cells." (PMID 37484809, 2023). "Moreover, knocking down NAT10 significantly inhibits the proliferation, invasion, and migration of cervical cancer cells." (PMID 39764566, 2025). "It found that high NAT10 expression is related to poor prognosis of patients with cervical cancer." (PMID 38233930, 2024). "NAT10 mediates HNRNPUL1 ac4C acetylation to promote cervical cancer progression." (PMID 39640362, 2024). "NAT10 is essential for cervical cancer cell growth and metastasis." (PMID 37484809, 2023). "Therefore, we selected HNRNPUL1 as the target gene of NAT10 in cervical cancer.RNA-Seq reads were then plotted and visualized in the Integrative genomics viewer (IGV) browser." (PMID 37484809, 2023). "What is the function of NAT10-mediated RNA ac4C modification in cervical cancer?" (PMID 37484809, 2023). "We speculate that in cervical cancer, NAT10-mediated ac4c modification regulates viral virulence by affecting HPV viral replication and stability." (PMID 37484809, 2023). "Thus, NAT10 is a newly identified prognostic biomarker for cervical cancer and a promising clinical target for this disease." (PMID 37484809, 2023). "Additionally, cytidine acetylation promotes translational efficiency through NAT10 mediated deposition of ac4C in the coding sequence (CDS) region of POLR2A mRNA transcript in human cervical cancer (HeLa cells)." (PMID 36149760, 2022). "Furthermore, we identified that expression of HNRNPUL1 is positively associated with expression of NAT10 in cervical cancer and that overexpression of HNRNPUL1 could rescue NAT10 knockdown-mediated tumor inhibition." (PMID 37484809, 2023). "We hypothesized that NAT10 expression could be a potential therapeutic focus for cervical cancer." (PMID 37484809, 2023). "This study indicates that NAT10 enhances the stability of HNRNPUL1 mRNA via ac4C modification, thereby promoting the progression of cervical cancer." (PMID 39764566, 2025). "In conclusion, NAT10 enhances the stability of HNRNPUL1 mRNA through ac4C modification, promoting the development of cervical cancer." (PMID 38233930, 2024). "CircMAST1 competitively binds to NAT10 to repress YAP mRNA acetylation and promotes cervical cancer progression." (PMID 39640362, 2024). "In conclusion, we show that ac4C modification by NAT10 promotes HNRNPUL1 mRNA stability and accelerates cervical cancer progression." (PMID 37484809, 2023). "Therefore, further investigation is warranted to determine whether HNRNPUL1, whose expression is up-regulated by NAT10, may either cause disordered DNA damage repair or promote HPV viral DNA synthesis and infection, thereby exacerbating cervical cancer progression." (PMID 37484809, 2023).
cervical carcinoma (continued). "NAT10 upregulates the ac4C modification of FOXP1 mRNA and increases its translation efficiency, ultimately upregulating the expression of GLUT4 and KHK, promoting increased glycolysis and sustained lactate secretion in cervical cancer cells." (PMID 39764566, 2025). "In contrast, acetylation of POU5F1 mRNA is not observed in human cervical carcinoma (HeLa) cells, indicating that the NAT10 targets different mRNA between normal and cancer cells." (PMID 40288646, 2025). "Therefore, NAT10 improves the stability of DDR1 mRNA by acetylation, promoting the growth, proliferation, invasion, and migration of cervical cancer cells." (PMID 38233930, 2024). "Combining multi-omics and bioinformatics analyses, we found that NAT10-mediated ac4C acetylation may affect the stability and expression of HNRNPUL1 mRNA in cervical cancer cells." (PMID 37484809, 2023). "Additionally, in cervical cancer, NAT10-mediated ac4C modification upregulates the expression of FOXP1, thereby reprogramming the glycolytic metabolic pathway to promote malignant progression of cervical cancer." (PMID 40303290, 2025). "NAT10/ac4C/FOXP1 axis was reported to facilitate immunosuppression and overexpression of FOXP1 was found to be positively related to the infiltration of activated CD4+ T cells and Tregs in cervical cancer, which supports our hypothesis." (PMID 38652109, 2024). "Thus, this study demonstrates that NAT10 contributes to cervical cancer progression by enhancing HNRNPUL1 mRNA stability via ac4C modification, and NAT10-ac4C-HNRNPUL1 axis might be a potential target for cervical cancer therapy." (PMID 37484809, 2023).
prostate carcinoma (16 papers, 2017 to 2025). A carcinoma that arises from epithelial cells of the prostate gland. "N-acetyltransferase 10 (NAT10), an enzyme responsible for ac4C acetylation, is implicated in cancer progression, though its specific biological function in prostate cancer remains insufficiently understood." (PMID 39648231, 2024). "In prostate cancer, NAT10 promotes metastasis by acetylating Keratin 8 (KRT8) mRNA to enhance its stability, downregulating E-cadherin and upregulating N-cadherin protein expression, thereby activating EMT." (PMID 40881352, 2025). "In prostate cancer, NAT10 was found to interact with DNA replication complexes and directly bind to cell cycle protein CDC6, participating in DNA replication processes." (PMID 40881352, 2025). "Specifically, KRT8 acts as a downstream target of NAT10, enabling it to perform mRNA acetylation modifications, which in turn influence the metastasis of prostate cancer." (PMID 40588654, 2025). "Previous studies have shown that NAT10 can promote the proliferation, migration, and metastasis of prostate cancer cells by regulating KRT8 through ac4C acetylation." (PMID 41203621, 2025). "A previous study has demonstrated that NAT10 promotes tumor malignant progression in prostate cancer." (PMID 41203621, 2025). "NAT10 inhibitors have been found to inhibit prostate cancer cell growth and proliferation, potentially because NAT10 can interact with CDC6 and bind to the DNA replication complex." (PMID 39817252, 2025). "Findings indicated significant upregulation of NAT10 in prostate cancer cells, enhancing their proliferative and invasive capacities." (PMID 39648231, 2024). "NAT10 can mediate prostate cancer (PCa) cell proliferation through high mobility group AT‐hook 1 (HMGA1)‐mediated cell cycle alterations." (PMID 39640362, 2024). "An ac4C modification score was also devised based on NAT10’s downstream targets, providing a novel predictive tool for evaluating immune infiltration and forecasting immunotherapy responses in patients with prostate cancer." (PMID 39648231, 2024). "This study clarifies NAT10’s role in prostate cancer and its effects on the tumor immune microenvironment." (PMID 39648231, 2024). "This study underscores NAT10’s pivotal role in modulating the prostate cancer immune microenvironment, offering insights into the immune desert phenomenon and identifying NAT10 as a promising therapeutic target for improving immunotherapy efficacy." (PMID 39648231, 2024). "NAT10 expression and clinical relevance were assessed through bioinformatics, RT-qPCR, and IHC analyses, comparing prostate cancer tissues with normal controls." (PMID 39648231, 2024). "NAT10 promotes proliferation, invasion, and migration of prostate cancer cells through DNA replication." (PMID 39640362, 2024). "The inhibition of NAT10 by Remodelin not only suppressed growth, migration, and invasion in vitro, but also the in vivo cancer growth of prostate cancer cells." (PMID 35743017, 2022). "Our data demonstrated that Remodelin, an inhibitor of NAT10, effectively inhibits the proliferation, migration, and invasion of PCa cells in both AR-positive and AR-negative prostate cancer cells." (PMID 35743017, 2022). "This also implied that the anti-neoplastic effects of Remodelin through NAT10 inhibition should be credited to the slowing down of DNA replication, which could consequently attenuate replication stress-associated genomic instability, and ultimately delay the progression of prostate cancer." (PMID 35743017, 2022). "The attenuation of proliferation by Remodelin was dose-dependent, indicating that the degree of NAT10 activity was closely related to the proliferation of prostate cancer cells." (PMID 35743017, 2022). "Consistent with our findings, clinical evidence has reported that NAT10 is partly overexpressed in melanoma tissues as well as neuroblastoma and prostate carcinoma derived from patients." (PMID 28880216, 2017).